MIR6851 (microRNA 6851)
Synonyms: hsa-mir-6851
Gene: MicroRNA gene on chromosome 9 (33,467,869 to 33,467,935, reverse strand). Ensembl gene ENSG00000275651.
Homologues: Orthologues: chimpanzee MIR6851 (100% identical).